CHI3L1 (chitinase 3 like 1)
Diseases named in the same sentence as CHI3L1 in open-access papers (continued):
Sharing a sentence is not in itself a finding about the gene and the disease.
glioma (continued). "Firstly, our data shows that direct targeting of proteins such as CD44, CHI3L1 or PARD3 may be ineffective at this stage of disease as they are already downregulated in glioma cells at the AOI." (PMID 25365423, 2014). "Overexpression of a splice variant of a transcription repressor NF-X, designated NFI-X3 (nuclear factor I-X3) enhanced YKL-40 expression in glioma cells by binding the regulatory elements of CHI3L1/YKL-40 promoter, activating transcription, promoting invasion, and migration." (PMID 24809021, 2014). "RelB knockdown cells displayed diminished RNA expression of the mesenchymal genes N-Cadherin/CDH2, SMAD2 and TGFβ3, as well as lower levels of YKL-40/CHI3L1, a biomarker of aggressive and recurrent gliomas that is very strongly associated with the mesenchymal glioma subtype." (PMID 23451236, 2013). "CHI3L1 is a member of the 18 glycosyl hydrolase family mapped at 1q32 genomic region, which is frequently amplified in different human cancers; amplifications were documented for glioma, esophageal squamous cell carcinoma, retinoblastoma." (PMID 23675241, 2011). "Moreover, CHI3L1 has been identified as a regulator of glioma cell invasion, migration, and growth." (PMID 38275876, 2024). "Therefore, EMP3 and CHI3L1 may affect the proliferation, apoptosis, and death of glioma cells by regulating CD44 and affecting TGF-β, ERK, Akt, and other pathways." (PMID 37887529, 2023). "Moreover, glioma cells with high expression of CHI3L1 were significantly enriched in NF-κB pathway." (PMID 36276655, 2022). "Therefore, U118MG and U251MG cells were treated with TNFα for up to 4 days to determine whether CHI3L1 expression was dependent on sustained activation of NF-κB pathway in glioma." (PMID 36276655, 2022). "Therefore, we propose that PPIC, EMP3 and CHI3L1 may be suitable as prognostic genes or therapeutic targets for high grade gliomas." (PMID 27801851, 2016). "SUV39H1 expression was positively correlated with the classic-like glioma subtype and markers such as NES and EGFR, with a lower correlation with mesenchymal-like markers like CD44 and CHI3L1." (PMID 40059829, 2025). "Chitinase-3 like-protein-1 (CHI3L1) binds to actinin alpha 4 (ACTN4) and NF-κB1 and enhances the NF-κB signaling by promoting the NF-κB subunit nuclear translocation to facilitate glioma progression." (PMID 39353894, 2024). "To ensure accuracy, we compared the gene expressions of POSTN, CHI3L1, SAA1, and MMP9 in these glioma cells using the CCLE database and confirmed that the classification was consistent." (PMID 39574472, 2024). "In another study based on the bioinformatic analysis, low-grade glioma patients with low expression levels of EMP3 and CHI3L1 had a better prognosis." (PMID 39033204, 2024). "Taken together, our evidence indicates that the predictive model constructed using POSTN, CHI3L1, SAA1 and MMP9 expression had significant prognostic value for patients with glioma." (PMID 39574472, 2024). "Previous studies have extensively documented the dysregulation and oncogenic properties of POSTN, CHI3L1, SAA1, and MMP9 in various cancer types, including gliomas." (PMID 39574472, 2024). "The genes POSTN, CHI3L1, SAA1, and MMP9 were screened to establish a predictive model, which exhibited a significant correlation with glioma prognosis and served as independent prognostic factors." (PMID 39574472, 2024). "This study elucidates Shikonin's capacity to effectively induce necroptosis in glioma cells, concurrently mitigating glioma stemness, as evidenced by diminished levels of stem cell markers, namely SOX2, CD44, CHI3L1, and CD24." (PMID 39619148, 2024). "We identified five critical genes (HOXA2, CHI3L1, POSTN, OASL, and ZNF474) with substantial roles in the glioma context." (PMID 38473752, 2024). "In comparison to other glioma subtypes, the GS2 exhibited higher expression levels of IBSP, PLA2G2A, NNMT, CA9, and MMP9, while the GS5 showed higher expression levels of CHI3L1, IGFBP2, EMILIN3, MEOX2, and PDPN." (PMID 38332637, 2024).
glioma (continued). "The expression levels of POSTN, CHI3L1, SAA1, and MMP9 were assessed in various glioma cell lines (U87, U251, U118, A172, T98G, SF295, LN229, and SF126) using qRT-PCR." (PMID 39574472, 2024). "A recent study demonstrated that two proteins, chitinase-3-like protein 1 (CHI3L1) and glial fibrillary acidic protein (GFAP), to be a potential CSF Biomarkers for glioma patients." (PMID 37633929, 2023). "The results showed that low-grade glioma patients with a low expression of EMP3 and CHI3L1 had a better prognosis, and EMP3 and CHI3L1 co-expression genes were correlated." (PMID 37887529, 2023). "HA was found to mediate glioma proliferation, progression, and invasion; it potentially promoted macrophage recruitment and M2 polarization through the IL-1/CHI3L1 and TGF-b/CHI3L1 axes." (PMID 36980765, 2023). "The results of qRT-PCR showed that both CHI3L1 and EMP3 were expressed at low levels in tumor tissues, and the expression levels decreased with an increase in the glioma grade." (PMID 37887529, 2023). "The results showed that low-grade glioma patients with low expression of EMP3 and CHI3L1 had better prognosis, and EMP3 and CHI3L1 co-expression genes were correlated." (PMID 37887529, 2023). "In conclusion, EMP3 and CHI3L1 can be used as prognostic indicators in low-grade gliomas, and the OS and DFS of patients with low EMP3 and CHI3L1 are significantly better than those of patients with high EMP3 and CHI3L1." (PMID 37887529, 2023). "Patients with low-grade gliomas with low EMP3 and CHI3L1 expression levels had significantly better OS." (PMID 37887529, 2023). "The mRNA levels of CHI3L1 are positively correlated with the WHO grade, IDH status, and TCGA subtypes of gliomas in TCGA and CGGA datasets." (PMID 36276655, 2022). "In particular, up-regulated CHI3L1 and CD44 are considered as markers of mesenchymal (MES) glioma 17 that predominantly manifested NF-κB activation." (PMID 36276655, 2022). "The top 20 network analysis indicated that PTX3, TIMP1, CHI3L1, LTF and IGFBP3 comprise a crucial role in gliomas progression." (PMID 36153549, 2022). "In fact, the expression of CHI3L1 increased with the tumor stage in both TCGA and CGGA glioma cohorts." (PMID 36276655, 2022). "Intriguingly, CHI3L1 binds to actinin alpha 4 (ACTN4) and NFKB1, and enhances the NF-κB signaling pathway by promoting the NF-κB subunit nuclear translocation in glioma cells." (PMID 36276655, 2022). "The Pearson correlation analysis indicated that strong positive correlations occurred between CHI3L1 and ACTN4, NFKB1 or NFKB2 in TCGA and CGGA glioma cohorts." (PMID 36276655, 2022). "Similar to the expression pattern of CGGA mRNAseq-325, CGGA mRNAseq-693 and TCGA merged GBMLGG cohorts, CHI3L1, MSN and TIMP1 were expressed higher in high-grade gliomas than in low-grade gliomas." (PMID 35332109, 2022). "Combined molecular groups based on the presence or absence of the four tumor markers (IDH status, 1p19q co-deletion status and CHI3L1 and NTRK2 expression levels) were used to classify the 671 glioma cases in the TCGA cohort according to prognosis." (PMID 30991699, 2019). "Taken together, the ELISA data confirm the cytokine array findings and implicate PDGF-AA, CHI3L1, IL-8, and ENG as secreted factors under negative regulatory control by neurofibromin in a subset of glial tumor cell lines in vitro." (PMID 29643433, 2018). "Analysis of The Cancer Genome Atlas confirmed a relationship between glioma NF1 status and ENG and CHI3L1 in tumor samples." (PMID 29643433, 2018). "Independent validation with glioma patients tissue (n = 70) and normal brain tissue (n = 19) found PPIC, EMP3 and CHI3L1 were up-regulated in glioma tissue." (PMID 27801851, 2016). "CHI3L1 suppressed E-cadherin but induced MMP9 and cell motility in glioma cells, all of them essential features of tumor cell invasion." (PMID 26425658, 2015).
glioma (continued). "TNF-α recruits p65 and p50 subunits of NF-κB to the CHI3L1/YKL-40 promoter, suppressing the expression of YKL-40 in glioma cell lines." (PMID 24809021, 2014). "RelB controls EMT and the expression of the mesenchymal genes in glioma, including YKL-40/CHI3L1, a secreted glycoprotein that is a prognostic indicator for poor survival in high-grade glioma as well as other cancers and inflammatory diseases." (PMID 23451236, 2013). "YKL-40 (also known as chitinase-3-like protein-1, CHI3L1) is heavily expressed at the protein level in the glioma proteome." (PMID 22957023, 2012). "Compared with the corresponding non-tumor tissues, CHI3L1 expression was significantly upregulated in various types of solid tumors, correlating with poor clinical outcomes including glioma." (PMID 39000203, 2024). "Additionally, Shikonin treatments resulted in diminished levels of glioma stem cell markers (SOX2, CD44, CHI3L1, and CD24) and the BMDM-derived TAM marker CD49D in glioma cells and subcutaneous animal models." (PMID 39619148, 2024). "Methods: using Oncomine, Gene Expression Profiling Interactive Analysis (GEPIA), the Chinese Glioma Genome Atlas (CGGA), cBioPortal, LinkedOmics, and other databases, 693 glioma patients were screened to analyze the relationship between EMP3 and CHI3L1 expression and prognosis in glioma patients." (PMID 37887529, 2023). "Interestingly, the enrichment score of the NF-κB pathway was positively correlated with the expression of CHI3L1 in glioma, especially in MES glioma which had the highest expression of CHI3L1." (PMID 36276655, 2022). "In glioma tissues of GBM, mesenchymal subtype cells have the high expression of mesenchymal subtype signature genes, including chitinase 3 like 1 (CHI3L1), collagen type V alpha 1 chain (COL5A1), fibronectin 1 (FN1), cyclin B1 (CCNB1), and maternal embryonic leucine zipper kinase (MELK)." (PMID 35158782, 2022). "The expression of CHI3L1/YKL-40 was also positively associated with the histological grade of the glioma, based on data from the Chinese Glioma Genome Atlas (CGGA) and the Gene Expression Database of Normal and Tumor Tissues (GENT)." (PMID 36408158, 2022). "Additionally, this model and four of its genes (CLECL5A, SERPING1, CHI3L1 and C1R) were found to be associated with immune cell infiltration, and further study demonstrated that these four genes might drive the hypoxic phenotype of perinecrotic GBM, which affects hypoxia‐induced glioma stemness." (PMID 33009892, 2020). "For the first time, we propose that CHI3L1 and NTRK2 could act as new biomarkers to improve the assessment of glioma prognosis." (PMID 30991699, 2019). "CHI3L1 acts not merely as a passive participant but as a key player in glioma pathophysiology, suggesting that its manipulation could open new therapeutic avenues." (PMID 39827337, 2025). "Therefore, the prognostic signature based on CHI3L1 and ORGI might hold a potential position in the development of treatment for gliomas." (PMID 39000203, 2024). "The predictive model constructed using four genes involved in macrophages and cancer cells, namely POSTN, CHI3L1, SAA1, and MMP9, holds promise in distinguishing high inflammation-hypoxia-immunosuppression microenvironment signatures and helps optimize trametinib selection for glioma treatment." (PMID 39574472, 2024). "Moreover, our study revealed that the expression levels of four genes (POSTN, CHI3L1, SAA1, and MMP9) were significantly elevated in glioma samples obtained from patients who experienced recurrence within one year after TMZ treatment, along with an increased risk score." (PMID 39574472, 2024). "In addition, in this paper, we only studied the relationship between the expression levels of EMP3 and CHI3L1 and the prognosis of glioma patients, without studying the specific pathway, which is also the focus of our research in the next stage." (PMID 37887529, 2023).
glioma (continued). "According to previous studies, CHI3L1 and EMP3 are two independent tumor predictors that are of great significance for the prognostic prediction of other tumors, and their expression levels may be related to the prognosis of glioma patients." (PMID 37887529, 2023). "However, the definite role of CHI3L1 and involved pathway in glioma progression are not completely understood." (PMID 36276655, 2022). "For example, the shRNA knockdown of CHI3L1, a gene identified for etoposide and cisplatin response in every tissue (but was not identified using LASSO for any of these drugs), has been shown to sensitize glioma cells to these two drugs, while its overexpression reduced their sensitivity." (PMID 31967990, 2020). "Similarly, the expression levels of key mesenchymal molecules including YKL40/CHI3L1 and FN1 (FIBRONECTIN 1) in GICs can be greatly induced by TNF-α treatment or overexpressing C/EBPβ, a transcription factor essential in mesenchymal transformation of gliomas." (PMID 27259253, 2016). "Additionally, our results showed that EMP3 and CHI3L1 expression was significantly higher in gliomas compared to non-tumor brain tissue." (PMID 27801851, 2016). "However, copy number profiling for human glioma does not show CHI3L1 gene amplification." (PMID 23675241, 2011). "The expression levels of EMP3 and CHI3L1 in wild-type IDH-1, non-1P19Q co-deletion, and MGMT non-methylated gliomas were higher than in others." (PMID 37887529, 2023). "In contrast to glioma stem cells, U87 cells showed no overexpression of stem cell markers, such as SOX2, ZEB1, ATXN1, ALCAM, CD9, ITGA7, CD44 and CHI3L1." (PMID 34680293, 2021). "Unlike CHI3L1 expression, the role of methylation in the NTRK family has not been demonstrated in glioma." (PMID 30991699, 2019). "High levels of CHI3L1 and EMP3 as well as FAPB7 and POSTN were reported as negative prognostic biomarkers in glioma." (PMID 29523123, 2018).
diabetes (84 papers, 2009 to 2025). "CHI3L1 plays a central role in inflammation and is associated with many diseases such as obesity, diabetes, and liver fibrosis." (PMID 41462520, 2025). "Abnormal CHI3L1 expression has been associated with multiple metabolic and neurological disorders, including diabetes, atherosclerosis, and Alzheimer’s disease." (PMID 38003338, 2023). "Understanding the roles of MaR1 and CHI3L1 in the inflammatory and fibrotic processes associated with diabetes and diabetic nephropathy may facilitate the identification of novel targets for early diagnosis and therapeutic intervention." (PMID 40731875, 2025). "In addition, increased systemic expression of CHI3L1 in patients with type 1 and/or type 2 diabetes mellitus was associated with progressing vascular damage in kidneys, as assessed by the level of albuminuria." (PMID 38110934, 2023). "CHI3L1 has been extensively studied in the context of diabetes and its complications, with evidence supporting its involvement in inflammation, tissue remodeling, and fibrosis." (PMID 40731875, 2025). "Both Chi3l1 and monocyte chemoattractant protein-1 (MCP-1) are involved in inflammatory responses, which are positively associated with the progression of diabetes and its complications." (PMID 39769202, 2024). "CHI3L1 expression is elevated in various inflammatory and chronic diseases, including obesity, diabetes, kidney disease, rheumatoid arthritis, inflammatory bowel disease, cancer, coronary artery disease, and acute ischemic stroke." (PMID 39026176, 2024). "Effective diagnostic methods for endocrine system-related diseases such as diabetes, obesity, insulin resistance, and Graves’ disease are essential, and Chi3l1 is widely reported to be a reliable biomarker." (PMID 39769202, 2024). "Elevated levels of CHI3L1 have been found in the plasma of both types of diabetes, and CHI3L1 levels are closely related to insulin resistance in T2D." (PMID 38003338, 2023). "CHI3L1 functions as an inflammatory regulator with relation to acute and chronic inflammation, and has played an important role in diabetes." (PMID 32929074, 2020). "Serum concentration of chitinase-3-like-1 (YKL-40), which is a novel marker of acute and chronic inflammation, was significantly higher in patients with periodontitis and diabetes compared to healthy groups." (PMID 32987652, 2020). "CHF is a complex disorder, often complicated by other comorbidities in which CHI3L1 is known to be elevated, such as arrhythmias, renal dysfunction, diabetes mellitus and hypertension." (PMID 31936828, 2020). "Our results showed that aortic CHI3L1 expression had a positive correlation with smoking, hypertension, and diabetes mellitus." (PMID 24729664, 2014). "We investigated the correlation between the relative expression levels of CHI3L1 and clinical criteria of atherosclerosis, including gender, smoking, hypertension, and diabetes mellitus." (PMID 24729664, 2014). "Elevated Chi3L1 expression in the retina implies a general increase in retinal inflammation with both diabetes and aging." (PMID 21633715, 2011). "Gender, smoking, hypertension, diabetes mellitus, and dyslipidemia are all risk factors that contribute to the development of atherosclerosis and some evidence indicates that circulating levels of CHI3L1 have relationships with smoking, hypertension, and diabetes mellitus." (PMID 24729664, 2014). "Exploratory analyses incorporating CRP and lipid measures argued against major confounding in controls and MCI, however, unrecorded variables such as body-mass index, metabolic syndrome, diabetes, or hypertension could have contributed to variability in peripheral CHI3L1 expression." (PMID 41425914, 2025). "Oleanolic acid (OA) administration partially decreases the level of Chi3l1 from 14.60 ± 1.00 ng/mL to 10.60 ± 0.90 ng/mL and alleviates renal damage-related inflammatory and oxidative profiles in diabetic rats, indicating its potential application in diabetes and diabetic nephropathy." (PMID 39769202, 2024).
diabetes (continued). "Moreover, Chi3l1 plays an important role in insulin resistance and diabetes, which closely correlates with glypican-4 (GPC-4), neuregulin-4 (NRG4), body mass index (BMI), the waist-to-hip ratio (WHR), and homeostasis model assessment of insulin resistance (HOMA-IR) in women with PCOS." (PMID 39769202, 2024). "In diagnosing NAFLD, CHI3L1 has been identified as a potential biomarker for NAFLD and diabetes-related liver fibrosis." (PMID 40821115, 2025). "In the aspect of diagnosing NAFLD, CHI3L1 has been identified as a potential biomarker for NAFLD and diabetes related liver fibrosis." (PMID 40821115, 2025). "Background and Objectives: This study aimed to investigate the relationship between Maresin-1 (MaR1), Chitinase-3-like protein 1 (CHI3L1), and inflammatory as well as hematological markers in patients with type 2 diabetes mellitus (T2DM) and diabetic nephropathy (DN)." (PMID 40731875, 2025). "One study analyzed these factors in patients with concurrent diabetes and eGFR < 60 mL/min/1.73 m2 by measuring levels of circulating tumor necrosis factor receptors 1 and 2 (TNFR1 and TNFR2), chitinase 3-like 1 (YKL-40) and kidney injury marker 1 (KIM1) in comparison with KFRT risk." (PMID 37371050, 2023). "Moreover, the significant alteration in levels of MMP1, MMP3, MMP11, CHI3L1 and VEGF-A in non-diabetic fibroblasts between day 3 and day 7 after the wound were all abolished in diabetic M1 fibroblasts, and their expression levels were also significantly lower in diabetes." (PMID 38270651, 2024).